CTHRC1 (collagen triple helix repeat containing 1)
Diseases named in the same sentence as CTHRC1 in open-access papers (continued):
Sharing a sentence is not in itself a finding about the gene and the disease.
gastric cancer (continued). "The upregulation of CTHRC1 is correlated with carcinogenesis, proliferation, invasion, and metastasis in numerous carcinomas, including gastric cancer." (PMID 35619651, 2022). "In this study, we systematically explored and validated the expression and prognostic value of CTHRC1 in gastric cancer by integrating the Cancer Genome Atlas (TCGA), Gene Expression Omnibus (GEO) and Genome Sequence Archive (GSA) datasets." (PMID 35928443, 2022). "The area under the curve (AUC) of CTHRC1 is 0.966, suggesting that CTHRC1 shows significant high sensitivity and specificity for the diagnosis of gastric cancer." (PMID 35928443, 2022). "In gastric cancer, we found CTHRC1 was highly co-expressed with many factors, such as ACVRL1, ANGPTL3, ANGPTL4, NOTCH4, VEGFB, VEGFC etc., which have been proved to play an important role in angiogenesis in various cancer." (PMID 35928443, 2022). "In this study, we presented a comprehensive catalog of CTHRC1 together with its prognostic value and related biological processes in gastric cancer to systematically investigate the expression pattern." (PMID 35928443, 2022). "Even though, the results of the present study reveal the molecular mechanisms of CTHRC1 in gastric cancer." (PMID 35928443, 2022). "High CTHRC1 expression signified poor OS (P = 0.00011) and FP (P < 0.0001) prognoses for patients with gastric cancer." (PMID 34702252, 2021). "The HIF-1α signaling pathway mediates the promotion of CThrC1 in the migration and invasion of gastric cancer cells." (PMID 34497636, 2021). "Let-7b inhibits cell proliferation, migration, and invasion through targeting CTHRC1 in gastric cancer." (PMID 31992202, 2020). "For instance, it has been reported that CTHRC1 was upregulated by promoter demethylation in gastric cancer." (PMID 29988590, 2018). "Aberrant overexpression of CTHRC1 has been observed in several kinds of malignant tumors including breast cancer, gastric cancer and melanoma." (PMID 25238260, 2014). "The expression of CTHRC1 protein in gastric cancer tissues is significantly higher than that in adjacent tissues, and there is a certain correlation between the expression of CTHRC1 protein and the prognosis of gastric cancer patients." (PMID 39132501, 2024). "The angiogenesis progress is complex in gastric cancer, where inhibiting CTHRC1 may decrease tumor blood vascular development." (PMID 35928443, 2022). "In conclusion, CTHRC1 expression may induce tumor associated macrophage infiltration though GRN/TNFRSF1A and AnxA1/FPR1 pathways and also tumor angiogenesis in gastric cancer." (PMID 35928443, 2022). "CTHRC1 expression and clinical characteristics in gastric cancer." (PMID 35928443, 2022). "In addition, a study elucidates that the molecule collagen triple helix repeat containing 1 (CTHRC1) enhances the tumor metastasis in animal model of gastric cancer via positively mediating HIF-1α expression." (PMID 35355804, 2021). "In relation to this, it has been pointed out that CTHRC1 could up-regulate the expression of HIF-1α in gastric cancer." (PMID 34512149, 2021). "Moreover, in gastric cancer, CTHRC1 was reported to promote tumor metastasis through the HIF-1α/CXCR4 signaling pathway." (PMID 34968391, 2021). "Besides, CTHRC1 is reported to be upregulated by promoter demethylation in gastric cancer and down-regulated by hypermethylation in hepatocellular carcinoma." (PMID 33628726, 2020). "As the second miRNA following lin-4 in Caenorhabditis elegans, Let-7b may directly target CTHRC1 and function as a tumor suppressor gene in gastric cancer." (PMID 32848510, 2020). "In addition, CTHRC1 expression may induce tumor associated macrophage infiltration though GRN/TNFRSF1A and AnxA1/FPR1 pathways and also tumor angiogenesis in gastric cancer." (PMID 35928443, 2022).
gastric cancer (continued). "In addition, we further explored the mechanisms of CTHRC1 in the progression of gastric cancer by focusing on the potential function of CTHRC1 in both macrophage infiltration and angiogenesis to identify a novel immunotherapy and angiogenesis target for gastric cancer treatment." (PMID 35928443, 2022). "In view of the relationship between the Wnt signaling pathway and gastric cancer, we identified the prognostic five genes signatures related to the Wnt pathway in this study, including CPZ, CTHRC1, DKK1, EGF, and GPC." (PMID 40296906, 2025). "Therefore, our results indicate that CTHRC1 plays a pivotal role in regulating the tumor microenvironment and predicts poor prognosis in gastric cancer, which suggests that CTHRC1 might be a promising novel immunotherapy and angiogenesis target for gastric cancer." (PMID 35928443, 2022). "The Cox proportional hazard model of COL8A1, COL10A1, CTHRC1, and FAP and six tumor-infiltrating immune cells in gastric cancer (TIMER)." (PMID 35910202, 2022). "Steady-state fibroblasts in cancer were described to progress towards activated CAFs expressing for instance CTHRC1, and COL11A1, similar to the differentiation trajectory we found for F13-CTHRC1 activated fibroblasts in gastric cancer." (PMID 36550535, 2022). "Intersection genes TREM2, CTHRC1, BGN, NOX4, GPX3, HEYL, and SFRP4 from the GSE72305 and GSE103236 datasets, which were differentially expressed in the normal gastric mucosa than in gastric cancer cells and in lymph node free to lymph node metastatic GC." (PMID 33976737, 2021). "On the other hand, prior research indicated that CTHRC1 enhanced cell adhesion, invasion, and metastasis but had no discernible impact on cell proliferation in gastric cancer, hepatocellular carcinoma, and pancreatic cancer." (PMID 37273536, 2023). "It was revealed that CTHRC1 overexpression was positively correlated with the T stage in gastric cancer but not lymph nodes metastasis from TCGA dataset." (PMID 35928443, 2022). "We performed Western blot analysis to explore whether the expression of CTHRC1 and LXN was altered in PRR11-KO SGC-7901 gastric cancer cells." (PMID 26252227, 2015).
breast carcinoma (33 papers, 2012 to 2025). "In particular, CTHRC1 was shown to be secreted from cancer-associated fibroblasts in breast cancer and promote invasion, EMT processes and activation of the Wnt/β-catenin pathway." (PMID 39748426, 2025). "In breast cancer patients with high periostin, the risk of bone metastases is enhanced by elevated CTHRC1 expression." (PMID 36190948, 2022). "Then our cohort study and further meta-analysis validated high expression of CTHRC1 was associated with aggressive clinicopathological features and poor clinical outcome of breast cancer patients." (PMID 28697793, 2017). "The significance of CTHRC1 in the pathogenesis of cancer is still unclear, but its overexpression has been reported associated with poor prognosis in solid tumors, gastric and breast cancer." (PMID 28427201, 2017). "In addition, our cohort study and further meta-analysis validated high expression of CTHRC1 was associated with aggressive clinicopathological features and poor clinical outcome of breast cancer patients." (PMID 28697793, 2017). "In addition, our cohort study and further meta-analysis corroborated high expression of CTHRC1 in primary tumors of breast cancer patients is associated with poor clinical outcome." (PMID 28697793, 2017). "In addition, CTHRC1 is implicated in breast cancer, suggesting that CTHRC1 expression in this type of tumour is associated with cancer tissue invasion and metastasis." (PMID 22321245, 2012). "The aberrant expression of CTHRC1 has been documented in various cancers, including breast cancer, stomach adenocarcinoma, non-small cell lung cancer, and colon adenocarcinoma." (PMID 38937712, 2024). "Treatment with breast cancer CM or direct co-culture with breast cancer cells upregulated Rankl, Mmp13, and Il6 and decreased Cthrc1 mRNA expression in MLO and Ocy454 cells." (PMID 38558984, 2024). "As an upstream regulator of E-cadherin’s N-glycosylation status, DPAGT1 can also upregulate CTHRC1 by increasing protein turnover, participating in the proliferation and migration of breast cancer cells." (PMID 39769140, 2024). "This when considered with the known role for MMP13 in bone metastasis of breast cancer strongly supports a role for CTHRC1-POSTN-MMP13 crosstalk in mediating the same." (PMID 36190948, 2022). "CTHRC1 is widely upregulated in several solid tumors, including melanoma, gastrointestinal cancer, breast cancer, thyroid cancer, liver cancer, and pancreatic cancer." (PMID 35307012, 2022). "Specifically, it has been reported that CTHRC1 regulates tumor progression through the CTHRC1/Wnt/β-catenin pathways in breast cancer, non-small cell lung cancer, and oral cancer." (PMID 35928443, 2022). "Proteomics data for breast cancers in revealing CTHRC1 overexpression with POSTN and MMP13 further strengthens the need to look at this gene network in other cancers." (PMID 36190948, 2022). "In breast cancer tumour samples CTHRC1 protein levels are significantly upregulated with POSTN and MMP13, further supporting the need to evaluate their crosstalk in cancers." (PMID 36190948, 2022). "CTHRC1 expression is increased in hepatocellular carcinoma, melanoma and breast cancer and in several studies increased mRNA and protein expression in tumors was associated with poor disease prognosis and survival." (PMID 33717164, 2021). "Overexpression of miR-30e or silencing of CTHRC1 suppresses proliferation, migration/invasion of breast cancer cells and promotes apoptosis." (PMID 34503172, 2021). "Results showed the expression level of CTHRC1 protein was step-increased in normal breast tissue, benign breast tumor tissue and breast cancer tissue, and its expression level in BC was frequently over-expressed in contrast with matched PBC." (PMID 28697793, 2017). "CTHRC1 expressions in breast cancer tissues and cells were assessed by qRT-PCR, western blot and immunohistochemistry." (PMID 28697793, 2017).
breast carcinoma (continued). "We also detected CTHRC1 protein in normal breast tissue, 5 benign breast tumor tissues and 18 paired breast cancer tissues with western blot." (PMID 28697793, 2017). "CTHRC1 mRNA expression level in breast cancer cells was significantly up-regulated, compared to that in MCF-10A, which was also verified by western blot." (PMID 28697793, 2017). "A total of 310 breast cancer patients were included in this meta-analysis, of which 176 were of high CTHRC1 expression and 134 were of low expression." (PMID 28697793, 2017). "To study the expression of CTHRC1 in human breast cancer cells and tissues, we performed qRT-PCR and western blot." (PMID 28697793, 2017). "The stromal expression of CTHRC1 has also been noted in breast cancer, where CTHRC1 is expressed in breast cancer cells as well as in the stromal myoepithelial cells and myofibroblasts." (PMID 26918341, 2016). "The expression of CTHRC1 was found to be induced by NFATC2, which has been implicated in the pathogenesis of many solid tumors, including pancreatic, lung, and breast cancers." (PMID 26918341, 2016). "Combined evaluation of CTHRC1 and periostin can serve as a potential marker for breast cancer bone metastasis." (PMID 26023718, 2015). "In breast cancer, CTHRC1’s involvement in these processes suggests that it could facilitate the structural changes necessary for cancer cells to invade surrounding tissues and form metastatic sites." (PMID 41280939, 2025). "Among 6 genes in the prognostic model, CTHRC1 was recognized as a novel gene involved in tissue remodeling and found to be overexpressed in carcinogenesis and metastasis of several solid cancers, as breast cancer (BC) and non-small cell lung cancer." (PMID 37404760, 2023). "In breast cancer, CTHRC1 gene and protein expression is upregulated with MMP13 and POSTN." (PMID 36190948, 2022). "Apoptosis of breast cancer cells is inhibited by CAF-EVs that reduce miR-30e expression to upregulate collagen triple helix repeat containing 1 (CTHRC1); this, in turn, activates the Wnt/β-catenin pathway to facilitate breast cancer development and progression." (PMID 34503172, 2021). "Finally, the analysis of the CPTAC dataset showed that the expression levels of the total CTHRC1 protein were enhanced in primary breast cancer, ovarian cancer, colon cancer, clear cell RCC, UCEC and LUAD compared with normal tissues." (PMID 34702252, 2021). "The IHC results showed higher expression of the CTHRC1 protein in tissues of renal, liver, colorectal, lung, and breast cancers than in normal tissues, and higher CTHRC1 expression in liver and renal cancer was distinctly associated with the patient prognosis (P < 0.001)." (PMID 34702252, 2021). "Furthermore, our cohort study and further meta-analysis validated CTHRC1 was an independent prognostic indicator for breast cancer patients." (PMID 28697793, 2017). "Next we detected CTHRC1 mRNA in normal breast tissue, 5 benign breast tumor tissues and 18 paired breast cancer tissues (9 cases with regional lymph node (LN) metastasis and 9 cases without) with qRT-PCR, and results were normalized with its expression in normal tissue." (PMID 28697793, 2017). "We supposed those breast cancer patients with CTHRC1 high-expression could be characterized into poor prognosis group, whose therapeutic effect of traditional strategies was not so good, and might be treated with strategies designed to up-regulate miR-30c." (PMID 28697793, 2017). "Taken together, we identified the role of miR-30c/CTHRC1 axis in breast cancer progression and demonstrated CTHRC1 may serve as a prognostic biomarker and therapeutic target for breast cancer." (PMID 28697793, 2017). "Collectively, all these data indicated CTHRC1 was up-regulated in breast cancer and it may be correlated with breast cancer metastasis." (PMID 28697793, 2017).
breast carcinoma (continued). "Taken together, these data fully demonstrated that CTHRC1 was closely correlated with poor survival and might be used as a novel independent prognosis biomarker for breast cancer." (PMID 28697793, 2017). "We also found high CTHRC1 expression was significantly associated with poor OS (RR = 3.04, 95% CI = [1.70, 5.47], P = 0.0002, fixed-effect) and RFS (RR = 2.64, 95% CI = [1.68, 4.16], P < 0.0001, fixed-effect) in breast cancer patients." (PMID 28697793, 2017). "Furthermore, there was an inverse correlation between the expression of miR-30c and CTHRC1 in breast cancer tissues (r = −0.56, P = 0.0143)." (PMID 28697793, 2017). "Currently, there is little information about the role of CTHRC1 in breast cancer progression." (PMID 28697793, 2017). "We found CTHRC1 was frequently up-regulated in human breast cancer cells and tissues." (PMID 28697793, 2017). "In the present study, we demonstrated that CTHRC1, negatively regulated by miR-30c, could promote breast cancer cell proliferation, invasion and migration and suppress cell apoptosis." (PMID 28697793, 2017). "Notably, breast cancer exhibited particularly high levels of CTHRC1." (PMID 40134434, 2025). "miR-30c could regulate CTHRC1 at a posttranscriptional level in breast cancer." (PMID 32848510, 2020). "Therefore, we hypothesized miR-30c/CTHRC1 axis might also exert its role by targeting GSK-3β/β-catenin signaling in breast cancer." (PMID 28697793, 2017). "Therefore, we suppose strategies designed to up-regulate miR-30c or down-regulate CTHRC1 may provide a promising method to alleviate breast cancer progression." (PMID 28697793, 2017). "Our data demonstrated that CTHRC1, negatively regulated by miR-30c, promoted cell proliferation, invasion and migration and suppressed cell apoptosis in breast cancer, which might be by activating GSK-3β/β-catenin signaling and inhibiting Bax/Caspase-9/Caspase-3 signaling respectively." (PMID 28697793, 2017). "Thus in future study, we will also focus on whether CTHRC1 regulates breast cancer progression by targeting EMT." (PMID 28697793, 2017). "However, the functional role of CTHRC1 and its related mechanism in breast cancer still remains unclear." (PMID 28697793, 2017). "Furthermore, expression of CTHRC1 has been reported in stromal cells of breast cancer." (PMID 24841500, 2014). "Osteopontin, gremlin-1, and collagen triple helix repeat-containing 1 (CTHRC1) influence migration, invasion, and EMT in breast cancer cells." (PMID 40136652, 2025). "In breast cancer, LINC00707 promotes CTHRC1 expression by inhibiting miR-30c, thereby enhancing tumor proliferation, invasion, and migration." (PMID 38850527, 2024). "CAFs can promote migration and invasiveness in breast cancer cells, as well as in the EMT, by secreting CTHRC1, with the PI3K pathway being one of the potential driving signaling pathways for CTHRC1." (PMID 39769140, 2024). "In addition, we found CTHRC1 could suppress breast cancer cell apoptosis." (PMID 28697793, 2017). "Compared with matched peri-tumor tissue of breast cancer (PBC), CTHRC1 mRNA in breast cancer tissue (BC) was frequently up-regulated." (PMID 28697793, 2017). "However, the functional role of CTHRC1 and its mechanism in breast cancer still remains unclear." (PMID 28697793, 2017). "Though CTHRC1 and POSTN upregulation in breast cancer is associated with poor prognosis, no direct interaction between them is reported." (PMID 36190948, 2022). "For example, CTHRC1 can inhibit tumor growth by suppressing glycolysis via adenosine triphosphate ATP generation, and extracellular acidification rate (ECAR), while increasing oxygen consumption rate OCR in breast cancer cells." (PMID 35313900, 2022). "Physical interaction networks however detected only COL3A1, suggesting it could be a gene of interest that CTHRC1, POSTN and MMP13 could use to regulate the tumour matrisome in breast cancers." (PMID 36190948, 2022).
breast carcinoma (continued). "Moreover, the univariate and multivariate analysis revealed that CTHRC1 expression was an independent prognostic factor for both OS and RFS of breast cancer patients." (PMID 28697793, 2017). "In this study, we also found it seemed that interfering the expression of CTHRC1 might change the morphology of BT549 cells when performing cell immunofluorescence, indicating CTHRC1 might also regulate EMT of breast cancer cells." (PMID 28697793, 2017). "Last but not least, in this study we identified CTHRC1 as an independent prognostic factor for breast cancer patients, suggesting it might be used for molecular classification of breast cancer." (PMID 28697793, 2017). "To clarify the clinical relevance of CTHRC1 expression in breast cancer, we performed IHC on breast cancer tissues of 121 breast cancer patients with tissue microarray, and then patients were dichotomized according to low (IRS ≤ 4) or high (IRS > 4) expression of CTHRC1." (PMID 28697793, 2017). "Moreover, CTHRC1 mRNA was significantly step-increased in benign breast tumor tissue, primary breast cancer tissues without LN metastasis and primary breast cancer tissues with LN metastasis." (PMID 28697793, 2017). "Firstly, CTHRC1 mRNA was detected by qRT-PCR in nontumorigenic MCF-10A breast epithelial cell line and breast cancer cells of different malignance, namely SK-BR-3, MDA-MB-231, MDA-MB-468, MCF-7, and BT549." (PMID 28697793, 2017).